LUM (lumican)
Diseases named in the same sentence as LUM in open-access papers (continued):
Sharing a sentence is not in itself a finding about the gene and the disease.
breast tumors (10 papers, 2006 to 2022). "The association between lumican expression and ER-positive breast tumors is supported by the findings from two studies." (PMID 19036156, 2008). "Altered expression of decorin and lumican is associated with breast tumors." (PMID 19036156, 2008). "In breast tumors, the expression of lumican was detected at the mRNA and protein levels, and it was concluded that lumican is the most important proteoglycan in breast tumors." (PMID 34885059, 2021). "In breast tumours, the expression of LUM was detected at the mRNA and protein levels, and it was concluded that LUM is the most important proteoglycan in breast tumours." (PMID 29088800, 2017). "A study on SLRP expression in breast tumors showed that lumican and decorin are the most frequently expressed SLRPs, whereas biglycan and fibromodulin are rarely detected." (PMID 25140302, 2014). "With increase in the stage of the breast tumors, the expression of lumican was decreased." (PMID 29568375, 2018). "Lumican was shown to be the most abundant proteoglycans in breast tumours." (PMID 28332606, 2017). "Furthermore, it has been proposed that lumican is differentially expressed during breast tumor progression." (PMID 25140302, 2014). "LUM belongs to the small leucine rich proteoglycan family of proteins that is involved in collagen fibril organization, in growth and migration of epithelial cells, in tissue repair, and in the progression of breast tumor." (PMID 24086418, 2013).
neuroblastoma (9 papers, 2018 to 2024). Neuroblastoma (NB) is the most common solid, extracranial childhood tumor. "The increased expression of intracellular Lumican in GB and neuroblastoma cells has been linked to the preservation of a stem-like phenotype, drug (temozolomide) resistance, and reduced overall survival." (PMID 39796053, 2024). "Although intracellular Lumican has been found to stimulate neuroblastoma cell migration, the effect of Lumican secretion by other cells on brain cancers has not been thoroughly evaluated." (PMID 39796053, 2024). "In the neuroblastoma, the silencing of the lumican gene in FOXO3 expressing IMR32 and SK-N-SH neuroblastoma cells or adding a FOXO3 inhibitor that restricted lumican transcription resulted in these cells’ reduced migration capacity." (PMID 34572532, 2021). "In a neuroblastoma model, lumican was a downstream mediator of FOXO3 transcription factor action and enhanced these cells’ migration." (PMID 34572532, 2021). "Glioblastoma and neuroblastoma CSCs produce high levels of lumican and decorin to acquire temozolomide resistance and a quiescent phenotype." (PMID 31334229, 2019). "Moreover, by inhibiting FOXO3 and weakening its binding with the LUM promoter, LUM expressions are suppressed, leading to reduced migration of neuroblastoma cells." (PMID 37692065, 2023). "Glioblastoma and neuroblastoma cells increase the mRNA and protein levels of DCN and LUM when cultured under CSC enrichment conditions." (PMID 36358747, 2022). "The DCN+/LUM+ CSC-like glioblastoma and neuroblastoma cells form secondary neurospheres when cultured in anchorage-independent conditions, and present a quiescent, less proliferative phenotype and temozolomide resistance." (PMID 36358747, 2022). "Notably, upon inhibiting FOXO3 by the small molecular weight compound repaglinide, the binding of FOXO3 to the LUM promoter was attenuated, abrogating the FOXO3-dependent lumican expression and decreasing neuroblastoma cell 2D- and 3D-migration." (PMID 34572532, 2021).
prostate carcinoma (9 papers, 2014 to 2025). A carcinoma that arises from epithelial cells of the prostate gland. "Specifically, decorin and lumican have shown inhibitory effects on prostate cancer progression, whereas the basement membrane proteoglycan perlecan has been identified as a tumor promoter." (PMID 39771106, 2024). "VCAN has been shown to be up-regulated in prostate cancer along with the PGs syndecan-1, perlecan, decorin, biglycan, neural/glial antigen, serglycin and lumican." (PMID 32354091, 2020). "Several proteoglycans have been found to be important in prostate cancer, including versican, decorin, biglycan, lumican, and syndecan-1, and data from a range of studies implicate proteoglycan alterations to prostate cancer cell survival and metastasis." (PMID 30893936, 2019). "Ectopic expression of lumican in the prostate cancer cell lines showed, decreased cell proliferation, migration and invasion." (PMID 29568375, 2018). "For example, an expression of collagens I, II, III, IV, fibromodulin, and proteoglycans (decorin, biglycan, lumican) in stromal cells, when grown in the presence of two metastatic prostate cancer cell lines PC3 and DU145, is significantly down-regulated." (PMID 24782989, 2014). "In prostate cancer, the inhibitory role of lumican was supported by several studies." (PMID 31963522, 2020). "Other PGs may also play a role, particular those that are up-regulated in prostate cancer, such as syndecan-1, perlecan, decorin, biglycan, neural/glial antigen 2, serglycin and lumican." (PMID 32354091, 2020). "Lumican is highly expressed within the stroma surrounding several solid tumors, such as lung ADC and prostate cancer." (PMID 34885059, 2021).
glioblastoma (8 papers, 2015 to 2024). The most malignant astrocytic tumor (WHO grade IV). "In glioblastoma and NB, LUM expression is associated with the maintenance of a quiescent, drug-resistant, stem-cell-like phenotype." (PMID 31861249, 2019).
bladder cancer (7 papers, 2019 to 2024). "Lumican was found to be overexpressed in bladder cancer tissues, and the depletion of Lumican inhibited bladder cancer cell proliferation and migration by suppressing MAPK signaling." (PMID 36361971, 2022). "By upregulating MAPK signaling, lumican (LUM) promotes the proliferation and migration of bladder cancer cells." (PMID 36732531, 2023).
Obesity (7 papers, 2019 to 2024). Accumulation of substantial excess body fat. "Our results suggest a role for the proteoglycan lumican in adipocyte dysfunction in obesity-associated DM." (PMID 36457256, 2022). "Lumican is a proteoglycan implicated in obesity, insulin resistance (IR), and adipocyte dysfunction." (PMID 36457256, 2022). "Lum, which encodes lumican, a proteoglycan identified to bind fibrillar collagen VI, is positively correlated with obesity." (PMID 31620014, 2019). "Culture of 3T3-L1 adipocytes in COL-I-based 3D microgels enriched in the proteoglycan, lumican (i.e., obesity conditions), induced a decrease in the number of LDs immunostained for Rab34, though no changes were observed in total Rab34 immunosignal per cell." (PMID 38183057, 2024). "In in vivo murine models of obesity (ob/ob and db/db), AT LUM levels correlate with impaired systemic metabolism." (PMID 36457256, 2022). "An emerging role for the small leucine-rich proteoglycan Lumican in metabolically driven nonalcoholic fatty liver disease sparks an interest in further understanding its role in diet-induced obesity and metabolic complications." (PMID 30409703, 2019). "Interestingly, ASPC3 was uniquely enriched for COL1A1, COL6A1, FN1, LOX, and LUM, which are fibrosis markers recently associated with a specific subset of PDGFRA+ progenitor cells in murine model of obesity." (PMID 36313560, 2022). "Possibly lumican may play a role in obesity-related cardiac remodeling and we observed that its level is elevated after weight loss, carrying the possible risk of fibrosis-related disturbances." (PMID 33716957, 2021). "To gain further insight into the role of Lumican in diet-induced obesity and insulin resistance without the influence of any developmental and behavioral functions of Lum, we over-expressed Lum in key visceral organs through a recombinant adeno-associated virus delivered intraperitoneally." (PMID 30409703, 2019).
asthma (6 papers, 2013 to 2023). "Other abnormalities in airway matrix structure in asthma, include a specific increase in the lumican and biglycan isoforms, which is also associated with tissue injury and worsening of the lung function (FEV1 ≤ 80% predicted)." (PMID 30979017, 2019). "Lumican displays a heterogeneous, diffuse, staining profile in the alveolar walls and peripheral regions of adult human lung and its sub-epithelial deposition is implicated in airway remodeling and counteracting the severity of asthma." (PMID 23350749, 2013). "Lung ECM remodeling in asthma is determined by the rate of ongoing deposition and degradation of proteins, including collagens I, III, and V, fibronectin, tenascin, lumican, and biglycan." (PMID 30979017, 2019).
Aortic dissection (5 papers, 2019 to 2023). Aortic dissection refers to a tear in the intimal layer of the aorta causing a separation between the intima and the medial layers of the aorta. "Therefore, the serum lumican level can be a potential diagnostic biomarker; however, more studies are required to further evaluate its usefulness in diagnosing acute aortic dissection." (PMID 33661915, 2021). "Therefore, they suggested that serum lumican can be a promising diagnostic biomarker for acute aortic dissection." (PMID 33661915, 2021). "Hence, a hypothesis was put forward: Lumican can be used as an early diagnostic marker for aortic dissection." (PMID 35910577, 2022). "In this sense, higher expressions of lumican have been found in the aorta of patients with chronic renal failure and in patients with aortic dissection." (PMID 37239052, 2023). "Previous studies have demonstrated that lumican can be a promising serum biomarker for diagnosing and predicting the severity of acute aortic dissection." (PMID 33661915, 2021). "According to Gu’s studies, the serum lumican level was high in acute aortic dissection." (PMID 33661915, 2021). "The relationship of aortic dissection and the serum lumican level may be explained by the pathophysiological mechanism in aortic dissection." (PMID 33661915, 2021). "Hence, the serum lumican level is higher in patients with acute aortic dissection because lumican distributed in the aortic wall is released into circulation." (PMID 33661915, 2021). "In general, TGF-β1 induced fibrosis participates widely in AAD mechanism such as endothelial malfunction, intima weakening, vascular wall injury and repair, therefore we came up with a hypothesis: the pathogenesis of aortic dissection maybe related to the Lumican-mediated TGF-β1 pathway." (PMID 35910577, 2022). "Nine proteins (Lumican, FGL1, PI16, MMP9, FBN1, MMP2, VWF, MMRN1, and PF4) related to the pathogenesis of aortic dissection were identified by David /Ease and String techniques as candidate biomarkers for verification test." (PMID 35910577, 2022).
atherosclerosis (5 papers, 2009 to 2025). A disease characterized by the build-up of fatty material and calcium deposition in the arterial wall resulting in partial or complete occlusion of the arterial lumen. "Circulating LUM levels are associated with carotid atherosclerosis plaque formation in hypertensive patients and is a promising molecular marker for atherosclerosis." (PMID 38474072, 2024). "Because both atherosclerosis and arterial calcification are linked to AD, LUM might participate in this pathogenesis through collagen fibrogenesis regulation and SMC migration and proliferation." (PMID 34310653, 2021). "Immunofluorescence (IF) staining of lesions from two different mouse models of atherosclerosis showed that modulated SMCs, marked by Lumican expression, were concentrated in the fibrous cap, spatially separated from MYH11+ SMCs in the media." (PMID 41107595, 2025). "LUM, also an SLRP family member, is particularly abundant in fibrotic tissues caused by pathogenesis such as atherosclerosis and heart injury." (PMID 34310653, 2021). "Nevertheless, in contrast with lumican and decorin, the evidence about the involvement of prolargin in either atherosclerosis or AS is very limited." (PMID 26620461, 2015). "Enhanced deposition of lumican has been observed in the intima of the atherosclerosis-prone internal carotid artery compared with the internal thoracic artery, a relatively atherosclerosis-resistant vessel." (PMID 20034393, 2009). "This enhanced deposition of LUM has important implications for the pathogenesis of atherosclerosis." (PMID 38474072, 2024). "Other studies on LUM expression have focused on atherosclerosis and arterial calcification." (PMID 34310653, 2021). "In the peripheral arteries, LUM expression was significantly higher in the intima of atherosclerosis-prone internal carotid artery than in the intima of the atherosclerosis-resistant internal thoracic artery, thereby indicating its role in atherosclerosis pathogenesis." (PMID 34310653, 2021).
endometriosis (5 papers, 2014 to 2024). The growth of functional endometrial tissue in anatomic sites outside the uterine body. "Moreover, cyto-hub gene analysis revealed that CSNK2A1, CSNK2A2, TOP1, PRKACA, RBM39 (plasma), ALB, ACTB, GAPDH, FN1, APOA1 (serum), S100-A9, CXCL1, IL1RN, CSTA, S100-A8 (menstrual blood) and THBS1, ALB, CD44, ANXA2, and LUM (urine) were the top 5 proteins expressed in women with endometriosis." (PMID 39061077, 2024). "First, the endometrial stromal cells show a relative deficiency of progesterone-sensitive gene markers associated with endometrial stromal cell decidualization in patients with endometriosis (e.g., IGFBP1, LEFTY2, LUM, DCN, etc.)." (PMID 36104692, 2022). "From the tissue profiling, TNC, CPM, TPM2, LUM and PAEP were selected for further testing as serological markers using samples from 87 women (control n = 21; pain control n = 21; endometriosis n = 45)." (PMID 30992697, 2019).
lung adenocarcinoma (5 papers, 2020 to 2024). A carcinoma that arises from the lung and is characterized by the presence of malignant glandular epithelial cells. "As an example of positive correlation, in lung adenocarcinomas the expression level of lumican in cancer cells correlated with pleural invasion and larger tumor size." (PMID 32548117, 2020). "COX7A1, PLAC9 and LUM are up-regulated in lung adenocarcinoma." (PMID 36357869, 2022). "Furthermore, lumican is highly expressed within the stroma surrounded several solid tumors such as prostate cancer and lung adenocarcinoma." (PMID 32548117, 2020). "In lung adenocarcinoma (ADC) and squamous cell carcinoma (SCC), the expression pattern and glycosylated form of lumican in cancer cells, as well as in stromal tissue correlated with the aggressiveness of ADC and SCC." (PMID 34885059, 2021). "This suggested that LINC02126 may play important roles in the development of lung adenocarcinoma by regulating the expression of DCN, COX7A1, PLAC9, LUM and MFAP4." (PMID 36357869, 2022).
Myocardial fibrosis (5 papers, 2019 to 2023). "Decorin and lumican are increased in myocardial fibrosis following pressure overload or myocardial infarction, while syndecan-4 contributes to myofibroblast differentiation in these settings." (PMID 32731636, 2020). "Although a pro-fibrotic function has been proposed for lumican, its expression was inversely correlated with degree of myocardial fibrosis in explanted failing hearts from patients." (PMID 31547598, 2019). "Likewise, lumican‐null mice are susceptible to aging or isoproterenol‐induced myocardial fibrosis, suggesting that lumican plays an antifibrotic role in the pathogenesis of myocardial fibrosis." (PMID 32910552, 2020). "Increased expression of lumican has been identified in myectomy samples from human patients with HCM, using proteomic analysis, which correlated strongly with myocardial fibrosis determined by LGE on cMRI." (PMID 37443910, 2023). "Therefore, contribution of lumican to myocardial fibrosis may be complex." (PMID 31547598, 2019).
pulmonary fibrosis (5 papers, 2013 to 2025). Chronic progressive interstitial lung disorder characterized by the replacement of the lung tissue by connective tissue, leading to progressive dyspnea, respiratory failure, or right heart failure. "Concerning pulmonary fibrosis, it has been shown an upregulation of LUM in the fibrotic lesions of patients with advanced disease, that promotes human monocyte differentiation into fibrocytes." (PMID 38322285, 2023). "They noted that transcripts characteristic such as fibronectin, lumican, thrombospondin, and collagen types I and VIII are common in both orbital and pulmonary fibrosis." (PMID 36295095, 2022).
aneurysm (4 papers, 2021 to 2025). Bulging or ballooning in an area of an artery secondary to arterial wall weakening. "In the in vivo study, we detected a gross lower expression level of CD68 and ARG1 (macrophage), Aggrecan (chondrocyte), OPN (osteoblast), ADIPQ (adipocytes), CD34 (mesenchymal cells), and LUM (fibroblasts) in the FAM3A-overexpressing aneurysm tissues compared with the matched Ad-sham tissues." (PMID 37660071, 2023). "Additionally, lumican showed decreased expression in medium-sized (5–5.5 cm) aneurysms compared with control patients." (PMID 36012466, 2022). "Therefore, they suggested that the serum lumican level is a potential biomarker for predicting future aneurysms in patients with bicuspid aortic valves." (PMID 33661915, 2021). "Another study demonstrated that lumican may predict future aneurysms in patients with bicuspid aortic valve undergoing aortic valve surgery." (PMID 33661915, 2021).
cardiac hypertrophy (4 papers, 2019 to 2023). "Since TGF-β isoforms are key mediators of fibrosis and cardiac hypertrophy across many species and upregulated by lumican and LOX in vitro, we explored their potential role in myocardial remodelling in feline HCM." (PMID 37443910, 2023). "Moreover, severe injury such as cardiac hypertrophy is displayed, which indicates the involvement of several DRGs of IL6, LUM, LRG1, PLG, with other molecules such as Alpha actinin, PDGF, Tgf beta, and TLR2 and TLR4." (PMID 32753925, 2020). "Calpain-2 catalytic subunit and lumican related to cardiac fibrosis, and mitogen-activated protein kinase 12 (MAPK12) related to cardiac hypertrophy, showed a significantly negative correlation with CO and TAPSE, and a significantly positive correlation with RV/BW." (PMID 35865003, 2022).
chronic renal failure (4 papers, 2021 to 2024). "Patients with chronic kidney disease had an increased risk of arterial calcification and exhibited concomitant increased LUM expression." (PMID 34310653, 2021). "LUM is a hub gene associated with the accumulation of ECM in diabetic nephropathy, a major cause of end-stage renal disease and a diagnostic biomarker of diabetic nephropathy." (PMID 38474072, 2024). "LUM has been identified to be overexpressed in VMSCs with chronic renal failure." (PMID 37711155, 2023).
diabetic nephropathy (4 papers, 2011 to 2024). "Altered regulation of LUM has been linked with abnormal collagen fibril morphology as a mediator of fibrotic disease in diabetic nephropathy." (PMID 22091387, 2011). "Nephroseq v5 webserver predicted the over expression of FN1, SPARC, LUM, VCAN, and POSTN with fold change of 2.808, 1.655, 6.25, 1.77, and 3.324 in diabetic nephropathy respectively." (PMID 34557161, 2021).